MYO9A (myosin IXA)
Description:
Myosins are actin-based motor molecules with ATPase activity. Unconventional myosins serve in intracellular movements. Regulates Rho by stimulating its GTPase activity in neurons. Required for the regulation of neurite branching and motor neuron axon guidance (By similarity).
Synonyms: FLJ11061; FLJ13244; MGC71859; CMS24
Tractability: Antibody: UniProt predicts a signal peptide or a membrane-spanning region; the Human Protein Atlas places it where antibodies can reach. PROTAC: ubiquitination databases record sites on it; its protein half-life has been measured.
Gene: Protein-coding gene on chromosome 15 (71,822,291 to 72,118,577, reverse strand). Ensembl gene ENSG00000066933.
Subcellular location: Membrane; Cytoplasm; Synapse; Cell projection, growth cone
Subcellular location (Human Protein Atlas): Plasma membrane
Pathways (Reactome):
Signal Transduction: RHOA GTPase cycle; RHOB GTPase cycle; RHOV GTPase cycle
Gene Ontology:
Molecular function: protein binding; actin filament binding; GTPase activator activity; microfilament motor activity; ATP binding; cytoskeletal motor activity
Biological process: cell junction assembly; establishment of epithelial cell apical/basal polarity; regulation of neuron projection arborization; regulation of small GTPase mediated signal transduction; visual perception; cell junction organization; intracellular signal transduction; postsynaptic specialization organization; signal transduction
Cellular component: actin filament; axonal growth cone; cytoplasm; cytosol; synapse; unconventional myosin complex; growth cone; membrane; myosin complex; Schaffer collateral - CA1 synapse
Genetic constraint (gnomAD): Loss-of-function variants: 79 observed, 230.03 expected, observed/expected ratio (o/e) 0.34, 90% interval 0.28 to 0.41. The upper end of that interval is the gene's LOEUF score, 0.41, which puts it in group 1 of 6, group 1 being the genes least tolerant of losing a copy. Missense variants: 2,377 observed, 2,775.5 expected, observed/expected ratio (o/e) 0.86, 90% interval 0.83 to 0.89. Synonymous variants: 895 observed, 968.42 expected, observed/expected ratio (o/e) 0.92, 90% interval 0.87 to 0.98.
Gene-disease validity (ClinGen):
ClinGen rates the evidence that MYO9A causes each of these diseases.
arthrogryposis syndrome (autosomal recessive): Limited.
Homologues: Orthologues: chimpanzee MYO9A (99% identical), macaque MYO9A (98% identical), dog MYO9A (92% identical), pig MYO9A (91% identical), mouse Myo9a (89% identical), rat Myo9a (89% identical), guinea pig MYO9A (87% identical), rabbit MYO9A (85% identical), zebrafish myo9aa (63% identical), tropical clawed frog myo9a (58% identical), zebrafish myo9ab (55% identical). Paralogues in human: MYO9B (37% identical), MYH7 (18% identical), MYH4 (18% identical), MYH6 (18% identical), MYH1 (18% identical), MYH3 (18% identical), MYH8 (18% identical), MYH2 (18% identical), MYH13 (18% identical), MYH7B (18% identical), MYH11 (17% identical), MYH9 (17% identical), and 32 more.
Diseases named in the same sentence as MYO9A in open-access papers:
MYO9A is named in the same sentence as 25 diseases in open-access papers, as found by Europe PMC text mining. Sharing a sentence is not in itself a finding about the gene and the disease. The quoted sentences say what the papers report.
Hydrocephalus (5 papers, 2014 to 2018). Hydrocephalus is an active distension of the ventricular system of the brain resulting from inadequate passage of CSF from its point of production within the cerebral ventricles to its point of absorption into the systemic circulation. "Mice deficient in myosin IXa develop severe hydrocephalus and it has been shown that myosin IXa plays an important role in epithelial differentiation and morphology." (PMID 24416302, 2014). "Myo9a knockout mice develop hydrocephalus and kidney dysfunction, which highlights the importance of MYO9A in epithelial cell morphology and differentiation." (PMID 30361512, 2018). "Myo9a knockout mice develop hydrocephalus and kidney dysfunction, highlighting the importance of Myo9a in epithelial cell morphology and differentiation." (PMID 26834556, 2016). "Myo9a homozygous knockout mice (Myo9a-/-) are characterized by high lethality, develop severe hydrocephalus within the first 2 weeks of life and display major motor defects." (PMID 26834556, 2016). "Notably, increased Rho kinase activity after deletion of myosin IXa can lead to hydrocephalus in mice." (PMID 28500065, 2017). "Increased RhoA activity after deletion of myosin IXa (Myo9a), a motor molecule with a Rho GTPase‐activating (GAP) domain, leads to hydrocephalus formation in mice." (PMID 28500065, 2017).
Cognitive impairment (2 papers, 2019 to 2026). Abnormal cognition is characterized by deficits in thinking, reasoning, or remembering. "Mild to severe cognitive impairment has been reported in patients carrying mutations in the SLC5A7 gene, DPAGT1 gene, SNAP25 gene, COL13A1 gene, MYO9A gene, MUNC13–1 gene, and in SCN4A-related CMS." (PMID 30808424, 2019).
focal segmental glomerulosclerosis (2 papers, 2022 to 2025). A renal disorder characterized by sclerotic lesions in the glomeruli. "Moreover, MYO9A has emerged as a candidate gene for focal segmental glomerulosclerosis, implicated in the regulation of podocyte adhesion and migration." (PMID 40564208, 2025).
diabetes (1 paper, 2021). "We examined Myo9A expression and distribution of S-nitrosylated proteins in kidneys from mice with streptozotocin-mediated diabetes and doxycycline-inducible, podocyte VEGF164 overexpression (DM- iVEGF164)." (PMID 34336885, 2021).
diabetic kidney disease (1 paper, 2021). Progressive kidney disorder caused by vascular damage to the glomerular capillaries, in patients with diabetes mellitus. "This study also suggested dysregulation of Myo9A expression in other experimental proteinuric diseases, such as nephrotic syndrome and diabetic nephropathy." (PMID 34336885, 2021). "Myo9A involvement in diabetic kidney disease has been suggested." (PMID 34336885, 2021). "To begin to understand the role of Myo9A in DKD progression we compared Myo9A expression in diabetic mice with mild vs. advanced diabetic kidney disease (DKD)." (PMID 34336885, 2021). "The relevance of Myo9A involvement in diabetic kidney disease is presently unknown." (PMID 34336885, 2021).
Hyperglycemia (1 paper, 2021). An increased concentration of glucose in the blood. "Therefore, we examined the effect of hyperglycemia on podocyte Myo9A expression and on S-nitrosylation." (PMID 34336885, 2021). "Alternatively, hyperglycemia and VEGF164-induced NOS uncoupling reduce NO availability, which in turn could influence Myo9A expression and SNO-Myo9A in diabetic glomeruli and thereby contribute to DKD progression." (PMID 34336885, 2021).
lymphoid cancers (1 paper, 2021). "Moreover, more than 2% of ~ 5000 samples from patients with haematopoietic and lymphoid cancers included in the COSMIC Release v94 database carried coding mutations in MYO9A, PALM2-AKAP2, MSI2 or CACNA1E (range 121–202 mutated samples per gene)." (PMID 34362951, 2021).
minimal change nephrotic syndrome (1 paper, 2019). "The numbers of endocytosed vesicles are increased under conditions of nephrotic syndrome, and these vesicles may be transported by motor proteins, including cytoplasmic dynein 1 and myosin IXa, whose expression is increased in glomeruli in cases of minimal change nephrotic syndrome." (PMID 31781392, 2019).
Obesity (1 paper, 2012). Accumulation of substantial excess body fat. "The MYO9A gene was in the BBS4 region of chromosome 15q22-q23, which might be important for obesity." (PMID 23241142, 2012).
type 1 diabetes (1 paper, 2021). "Using an experimental type 1 diabetes (T1D) mouse model we determined that Myo9A expression in the kidney is decreased in diabetic mice with advanced DKD, while in diabetic mice with mild DKD Myo9A expression is not different from non-diabetic mice." (PMID 34336885, 2021).
cancer (3 papers, 2017 to 2024). A tumor composed of atypical neoplastic, often pleomorphic cells that invade other tissues. "According to the mouse insertional mutagenesis experiments, three of these genes (DMD, MYO9A, and COL5A2) have been identified as cancer-causing genes." (PMID 28938601, 2017). "Additionally, MYO9A shows promise as a powerful predictive biomarker for cancer prognosis and immunotherapy response in CRC." (PMID 38858644, 2024). "Furthermore, some of the positively selected genes might also be related to cancer, such as DMD, MYO9A, and COL5A2, which have been identified as cancer-causing genes based on mouse insertional mutagenesis experiments." (PMID 28938601, 2017).
tumor (3 papers, 2018 to 2024). "MYO9A was overexpressed in the tumor containing the ANXA2-MYO9A fusion, which supports transcriptional activation as the oncogenic mechanism for this gene fusion." (PMID 30361512, 2018). "MYO9A may contribute to tumor suppression, while downregulation of MYO9A may impact CRC tumorigenesis by disrupting epithelial polarity and architecture, resulting in a worse prognosis in CRC." (PMID 38858644, 2024). "WGS data of this tumor revealed that g.chr15: 60,656,550 (ANXA2 intron 4) was aberrantly fused to g.chr15: 72,157,966 (MYO9A intron 32), which was confirmed by PCR sequencing analysis of genomic DNA." (PMID 30361512, 2018).
neurodegenerative disease (1 paper, 2020). A disorder of the central nervous system characterized by gradual and progressive loss of neural tissue and neurologic function. "MYO9A is an unconventional myosin responsible for the regulation of Rho GTPase activity within neurons, which in turn regulates neuronal morphology and function; for these reasons, the Rho family has been a recent therapeutic target for neurodegenerative diseases such as AD." (PMID 32429992, 2020).
neuromuscular disease (1 paper, 2019). "Therefore, this study highlights a role for MYO9A at the NMJ, the first unconventional myosin motor protein associated with a neuromuscular disease, and provides a potential mechanism of action of MYO9A-pathophysiology." (PMID 31394789, 2019).
MYO9A also shares sentences with these, for which no sentence is quoted: Anxiety (1 paper); cervical cancer (1); colorectal cancer (1); congenital myasthenic syndrome (1); depression (1); melanoma (1); membranous nephropathy (1); metabolic syndrome (1); nephrotic syndrome (1); Noonan syndrome (1); rheumatoid arthritis (1).